WNT5A (Wnt family member 5A)
Diseases named in the same sentence as WNT5A in open-access papers (continued):
Sharing a sentence is not in itself a finding about the gene and the disease.
cancer (continued). "Wnt5a is classified as a non-transforming Wnt family member that plays complicated roles in oncogenesis and cancer metastasis." (PMID 22655072, 2012). "Other cancer studies revealed a downregulation of the tumour suppressor Wnt5a, related to the non-canonical pathway, the deletion or reduced expression of which can occur in several cancers including sarcomas." (PMID 22550422, 2012). "In low-grade cancers (Gleason 3+4 or less) and in high-grade cancers (Gleason 4+3 or higher), the high expression of Wnt5a protein was 38% and 48%, respectively, which was not significantly different (P = 0.183, Fisher's exact test)." (PMID 23342259, 2012). "Wnt5a is a non-canonical secreted glycoprotein of the Wnt family that plays an important role in cancer development and progression." (PMID 22039506, 2011). "Whereas canonical Wnt signaling is required for G1 cell cycle progression in CRC, the non-canonical ligand WNT5A negatively regulates proliferation but promotes migration in various cancer types." (PMID 17897439, 2007). "In cancer, upon exposure to microbial challenges, the activation of dectin-1, a receptor in macrophages, stabilises β-catenin and stimulates the increased secretion of noncanonical Wnt5a." (PMID 38136392, 2023). "The host response to infection causes differential expression of Wnt signaling molecules, in particular overexpression of canonical ligands such as Wnt7b and non-canonical ligands such as Wnt5a, in infiltrating macrophages activated in both inflammation and cancer." (PMID 37512809, 2023). "In addition, the correlation between WNT5A and the CTGF/ANKRD1 signature as a readout for YAP/TEAD activity might be correlated with cancer progression in both TGCT and PAAD." (PMID 33643710, 2021). "PIK3CA-mutant cancers displayed higher expression of 12 of the 17 Wnt genes compared to PIK3CA wild-type tumors, including five Wnt target genes (LEF1, MYCN, FZD7, SFRP2, and TNFRSF11B) and seven Wnt signaling components (TCF7L1, TCF7L2, CTNNB1, FZD4, SFRP1, WNT5A, and MSX2)." (PMID 34035258, 2021). "Importantly, as no prior study have shown the association between Wnt5a and CYP in any cancer, these results are novel." (PMID 34047951, 2021). "In addition, the non-canonical Wnt/PCP pathway (FAT2, CELSR1, WNT5A), known to suppress early-staged cancers by regulating cell adhesion or migration, was downregulated in group 3." (PMID 30699951, 2019). "Wnt5a is undoubtedly the most studied non-canonical Wnt ligand in cancer." (PMID 31510045, 2019). "Wnt5a is an important regulator of both the Wnt/PCP and Wnt/β-catenin pathways, playing a prominent role in neuronal stem cells and nervous system development, and is an important regulator of tumorigenicity of many human cancers, including neuronal derived ones." (PMID 30271945, 2018). "Novel therapeutics for Wnt5a driven cancers are lacking in the clinic." (PMID 29648538, 2018). "Furthermore, we show that the ligands Wnt5a/b are upstream regulators of the non-canonical signature and moreover regulate proliferation of cancer cells in a β-catenin-independent manner." (PMID 29453334, 2018). "Thus, the downstream effects of WNT-5A are highly context dependent and the differential signaling mechanisms it engages may account for the opposing functions of WNT-5A in cancer." (PMID 26514730, 2016). "These secreted regulatory proteins may lead to activation of both canonical (Wnt3a) and non-canonical (Wnt5a) Wnt signaling pathways in cancer." (PMID 27323822, 2016). "Therefore, the noncanonical Wnt signaling, such as Wnt5a, has been suggested as potential therapeutic targets in cancers." (PMID 27895670, 2016). "In addition, our data showed that patients with double positive cancers (ROR2+/Wnt5a+) had significantly worse survival than those with double negative cancers (ROR2-/Wnt5a-)." (PMID 26305508, 2015).
cancer (continued). "Thus, Src was a major component of SFKs in A549 and Calu-6 cells and the SFK activity was reduced by knockdown of Wnt5a but not clathrin in these cancer cells." (PMID 25622531, 2015). "Although the entire mechanism by which Wnt5a stimulates cancer cell proliferation is still not fully understood, SFKs might be involved in this pathway." (PMID 25622531, 2015). "Wnt5a, a typical non-canonical Wnt protein, is related to a variety of malignant tumors." (PMID 26305508, 2015). "Moreover, Wnt5a mRNA level in H. pylori-positive cancer tissues was higher than that in H. pylori-negative ones." (PMID 24993819, 2014). "Wnt5a is a noncanonical signaling member of the wingless-related/mouse mammary tumor virus integration family, which is involved in a wide range of cellular processes, particularly in cancer development and metastasis." (PMID 24944588, 2014). "Wnt5a is a key initiating factor in the non-canonical pathway, but its role in cancer is not known." (PMID 24564183, 2014). "Despite this similarity in proportion of low- and high-grade cancers, we could not find the same predictive ability of Wnt5a expression as they found in their study." (PMID 23342259, 2012). "For example, we do not know (i) Whether the increase in WNT5A gene transcription results in increased Wnt5A protein expression in malignant tumors?" (PMID 20454608, 2010). "In the cancer cell, for instance, where Wnt-5a has been silenced, introduction of a Wnt-5a mimic may concomitantly activate non-canonical signaling, which also has cancer-promoting properties." (PMID 19603030, 2009). "However, on account of the inability of Wnt-5a to transform cells, its role in cancer promotion was not immediately apparent." (PMID 19603030, 2009). "However, the cancer cell lines treated with cytochalasin D showed no changes in cell morphology or Wnt5a induction, suggesting disruption of this regulatory pathway in cancer." (PMID 9716023, 1998). "However, the non-canonical Wnt pathway, particularly Wnt5a, also plays a crucial role in cancer." (PMID 33643710, 2021). "Although in vitro models (cancer cells/adipocytes) confirmed that phenotype of CAAs may be triggered directly by cancer cells, and some candidate molecules released by tumor cells such as TNF-α, Wnt3a, Wnt5a, and MMP11 have been proposed, the exact mechanism remains elusive." (PMID 33916703, 2021). "However, the precise molecular role of Wnt5a in cancer has not been fully clarified." (PMID 32195251, 2020). "Therefore, our results suggest that both regulatory macrophages and dexa-tolDC might be triggering similar tolerogenic mechanisms, probably through the STAT3 and Wnt5a signaling pathway, as its interaction with CD163 has already been reported in cancer studies." (PMID 30297862, 2018). "Further investigation of Wnt5a and the noncanonical Wnt signaling pathways may contribute to revealing the occurrence, development and metastasis of tumors, which may provide novel targets for the diagnosis and treatment of cancer." (PMID 24944588, 2014). "Therefore, there is a considerable body of data that supports the hypothesis that Wnt-5a can advance particular cancer types, but is unlikely to be a primary or initiating event." (PMID 19603030, 2009). "In addition, investigation of how Wnt5a may modulate proteasomal degradation of YAP—including its effects on E3 ligase interactions and ubiquitination—will be necessary to comprehensively delineate the upstream regulation of YAP stability in trastuzumab-resistant cancers." (PMID 40542295, 2025). "Particularly, the non-canonical ligands WNT5A and WNT11 were shown to contribute to metastasis in several cancer entities." (PMID 36982422, 2023). "In previous reports, Wnt5a induce EMT and potentiate metastasis across multiple cancer types through non-canonical mechanisms and also mediate gemcitabine resistance in PDAC via upregulation of ABCG2." (PMID 34794402, 2021).
cancer (continued). "Wnt5a, a representative Wnt ligand of the non-canonical pathway and FZD7, a receptor for secreted WNT proteins, promote cancer cell metastasis, EMT and chemoresistance in several cancers." (PMID 31671889, 2019). "In contrast, the metaplastic cell line CP-A and the carcinoma cell lines OE33 and OE19 did not express Wnt5a." (PMID 30841855, 2019). "WNT5A is a non-canonical member of the WNT family and is a tumor autocrine/paracrine factor highly expressed in many cancer types." (PMID 29882812, 2018). "Patients with low-grade cancers, displaying high-Wnt5a protein expression and positive SMS have similar relapse-free time after RP compared to patients with low-Wnt5a staining and negative SMS." (PMID 23342259, 2012). "Elevation of Wnt5a in HB2, a normal breast epithelial cell line, was linearly correlated with cell density, but this did not occur in cancer cell lines." (PMID 9716023, 1998). "Combining pseudotime, RNA velocity–PAGA, cellular entropy, and regulon analysis in stromal cells reveals a cancer-specific rewiring of fibroblasts, where STAT1, TGF-β, and inflammatory signals induce a noncanonical WNT5A program that maintains the stromal inflammatory state." (PMID 35687691, 2022). "More importantly, WNT5A correlates with a YAP/TEAD signature and pJNK/pAKT in testicular germ cell cancer, thus providing potentially novel evidence for a role of the non-canonical Wnt pathway in this cancer type." (PMID 33643710, 2021). "Mechanistically, Wnt5a could regulate ATP-binding cassette, subfamily B (ABCB1, P-gp, and MDR1) expression in multidrug-resistant cancer cells through activation of the noncanonical protein kinase A (PKA)/β-catenin pathway." (PMID 27895670, 2016). "Besides, non-canonical WNT pathways, especially the typical WNT5A and WNT11 pathways, are reported to be involved in several carcinogenic and cancer progression pathways." (PMID 23094073, 2012). "Although not related to Wnt5a signaling, SFRP3 has been shown to reverse EMT, decrease activity and expression of matrix metalloproteases and decrease activation of β-catenin in other types of cancer." (PMID 21494614, 2011).
infection (39 papers, 2007 to 2025). The state of being infected such as from the introduction of a foreign agent such as serum, vaccine, antigenic substance or organism. "The high level of morbidity/mortality in the infected Wnt5A heterozygous mice as compared to the wild-type is quite likely due to the weakened ability to combat pathogenic conditions associated with infection." (PMID 39140737, 2024). "Wnt5A wild-type and heterozygous mice were afresh used to study how the Wnt5A dosage–gut commensal axis-associated B-cell repertoire correlates with infection." (PMID 39140737, 2024). "Overall, these results suggest that a gut Wnt5A–microbiota axis is intrinsically associated with the maintenance of gut B-cell repertoire and protection from infection." (PMID 39140737, 2024). "We investigated the influence of a Wnt5A–gut microbiota axis on gut B-cell repertoire and protection from infection, having previously demonstrated that Wnt5A in association with gut commensals helps shape gut T-cell repertoire." (PMID 39140737, 2024). "The augmented levels of Wnt5A dependent ROS and iNOS, demonstrated separately in the spleens of infected mice and in isolated macrophages after infection are in concurrence with parasite killing linked with Wnt5A signaling." (PMID 35197983, 2022). "This concept is corroborated by the regulatory effect of Wnt5A signaling on infections by pathogenic bacteria such as Streptococcus pneumoniae, Pseudomonas aeruginosa, and Mycobacterium tuberculosis." (PMID 33664738, 2020). "Human cytomegalovirus (HCMV) infection of human foreskin fibroblasts was associated with WNT5A and WNT5B downregulation, whereas HCMV infection elevated WNT2 expression in human mesenchymal stem cells." (PMID 31781093, 2019). "The situation perhaps is guided by the extent of Wnt5A signaling in macrophages, as we observed inhibition of infection by pathogenic microbes through activation of Wnt5A signaling and increased infection through its blockade." (PMID 31736969, 2019). "Wnt5A signaling suppresses infection by the parasite Leishmania donovani, the causative agent of visceral leishmaniasis by blocking the sustenance of L. donovani containing parasitophorous vacuoles within macrophages." (PMID 31736969, 2019). "A similar alteration in cell-associated Wnt5A and secreted Wnt5A was also obtained after PA infection of RAW 264.7 cells at MOI: 10 with PA, at three different time points (1, 3, and 6 h)." (PMID 29686674, 2018). "Our observations that pathogenic bacterial burden was increased in different infection models upon inhibition of Wnt5A signaling suggested a role for Wnt5A signaling in antibacterial immunity." (PMID 29686674, 2018). "In view of the functional interdependence of B and T cells (4, –, 6) and the influence of gut microbiota on B-cell differentiation, we presently explored the possibility of an association of a Wnt5A–gut commensal axis with the shaping of gut B-cell repertoire and thereby protection from infection." (PMID 39140737, 2024). "We undertook this study to understand if Wnt5A signaling regulates host susceptibility vs. resistance to infection caused by important human pathogenic bacteria and whether Wnt5A itself, is affected by the load of bacterial infection." (PMID 29686674, 2018). "The Wnt signaling pathway is involved in a variety of life processes, and Wnt5a expression is increased during infection and inflammation, which can regulate the production of the immune anti-inflammatory factor IL-1028." (PMID 39920853, 2025). "Our findings reveal that a Wnt5A–gut commensal axis indeed influences the gut B-cell repertoire and resistance of the host toward infection." (PMID 39140737, 2024). "Wnt5A heterozygous mice, furthermore, exhibited notably higher than the wild-type levels of morbidity and mortality following infection with Salmonella typhimurium, a common gut pathogen." (PMID 39140737, 2024).
infection (continued). "Similar to recombinant WNT5A, fibroblasts infected with WNT5A-expressing adenovirus (Adv) at a multiplicity of infection (MOI) of 80 exhibited an upregulation of collagen type I and α-SMA." (PMID 38747285, 2024). "In essence, Wnt5A heterozygous mice, which retained relatively low level of Wnt5A after infection, developed more intense disease after L. donovani infection as compared to the wild type controls." (PMID 35197983, 2022). "Wnt5A treatment prior to infection also correlated with slightly low plasma levels of IL-4, which has been reported to worsen the disease outcome." (PMID 35197983, 2022). "More specifically, RNA silencing of Fzd5 or its ligand Wnt5a results in a highly significant reduction of infection, suggesting the necessity of Wnt5a-Fzd5 signaling for E. chaffeensis entry and survival." (PMID 33912170, 2021). "Prior to infection, the macrophages were activated with either Wnt5A conditioned medium prepared from Wnt5A overexpressing L cells (L5A) or treated with L cell conditioned medium (L) as control." (PMID 33664738, 2020). "Conversely Wnt5A signaling opposes infection by E. coli K1 facilitating its clearance because K1 is incompatible with Wnt5A signaling and decreases F-actin assembly." (PMID 33664738, 2020). "Bacterial CFU retrieved from the infected cells before and after 3 h incubation depicted the effect of inhibition of Wnt5A assisted actin assembly on infection outcome." (PMID 33664738, 2020). "Incidentally, like K1 infection, infection by Pseudomonas aeruginosa (PA14) also causes decrease in polymerized actin, and activation of Wnt5A signaling leads to bacterial killing." (PMID 33664738, 2020). "Taken together, our study illustrates that the state of activation of the Wnt5A/Actin axis in the context of the incumbent bacteria is crucial for directing host response to infection." (PMID 33664738, 2020). "WNT pathway activation (e.g., by Wnt5a) upon infection with M. bovis BCG has been reported to interfere with IFNγ-induced activation of autophagy in mouse macrophages, a process facilitated by arachidonate lipoxygenase." (PMID 31781093, 2019). "We also have evidence for up-regulation of non-canonical Wnt signalling as seen in higher pup brain expression of Wnt5a, its associated receptors (RoRa and b, PLC) and ion channels (KCNQs and VGCC) in response to maternal infection." (PMID 30862816, 2019). "Expression of Wnt5a and Fzd4 by murine macrophages marginally increased upon infection with S. aureus." (PMID 31781093, 2019). "It was found that infection with pathogenic bacteria, including BCG, S. flexneri and Listeria monocytogenes stimulate the expression of Wnt ligand Wnt5a, receptor Fzd4 and co-receptor Lrp5 to bring about the inhibition of IFNγ-induced autophagy." (PMID 31497020, 2019). "Wnt5a-induced killing within the first hours of infection was suggested to be mediated by Rac-1 and Dvl." (PMID 31781093, 2019). "T. cruzi early infection increases expression of Wnt5A, 3A, several Frizzled receptors, and Wnt signaling intermediates." (PMID 31736969, 2019). "In contrast, RAW264.7 macrophages exposed to recombinant Wnt5a displayed a more rapid decline in viable intracellular S. pneumoniae and P. aeruginosa within the first 2–3 h of infection." (PMID 31781093, 2019). "survival is possibly based on the nature of the tussle between host induced and pathogen induced modulations (conformations) of actin and actin binding proteins in the very early stages of infection wherein host Wnt5A signaling plays a fundamental role." (PMID 31736969, 2019). "Wnt5A mediated cytoskeletal alterations correlate with parasitophorous vacuole degradation and inhibition of infection." (PMID 31736969, 2019). "Wnt5A-Rac1-Rho mediated cytoskeletal alteration promotes enhanced fusion of parasitophorous vacuole with lysosome which helps in restraining infection." (PMID 31736969, 2019).